BMAL1 (basic helix-loop-helix ARNT like 1)
Diseases named in the same sentence as BMAL1 in open-access papers (continued):
Sharing a sentence is not in itself a finding about the gene and the disease.
glioblastoma (31 papers, 2020 to 2025). The most malignant astrocytic tumor (WHO grade IV). "Concerning caspase activity regulation, it has been shown, in glioblastoma cells, that the activity of caspase-3/7 was higher at the peak of Bmal1 expression and that Bmal1 loss resulted in ablation of the rhythm in TMZ-induced caspase activity." (PMID 37504857, 2023). "Here, we addressed the function of BMAL1 in U87MG glioblastoma cells with two approaches—loss and gain of function." (PMID 32231148, 2020). "In this study, we addressed the role of BMAL1 in glioblastoma cells in vitro with two basic approaches, loss and gain of function." (PMID 32231148, 2020). "Indeed, using a wound healing assay, it was observed that BMAL1 overexpression led to inhibit glioblastoma cells' invasion and migration, which were linked to reduced MMP‐9 expression via AKT inhibition." (PMID 38336976, 2024). "Likewise, we observed that the level of cyclin B was downregulated in BMAL1-overexpressing glioblastoma cells, which likely caused the increase in the sub-G1 population by apoptosis." (PMID 32231148, 2020). "For example, reducing the expression of BMAL1 or CLOCK in glioblastoma stem cells (GSCs) can induce cell cycle arrest and trigger apoptosis." (PMID 40046513, 2025). "FABP7 epigenetically reprograms to suppress immune-related genes (e.g., LPCAT3) while upregulating ferroptosis-resistant genes (e.g., BMAL1), helping glioblastoma cells evade immune clearance." (PMID 40717587, 2025). "The core circadian regulator CLOCK/BMAL1 complex is reported to sustain cancer stem-like traits and immunosuppression features of glioblastoma." (PMID 39054537, 2024). "Treatment of U87MG glioblastoma cells with BMAL1 small interfering RNA (siRNA) has been shown to promote the proliferation of tumour cells." (PMID 38336976, 2024). "Downregulating BMAL1 or CLOCK triggers reduced cell proliferation rate in the glioblastoma stem cells (GSCs), hepatocellular carcinoma (HCC) cells, and leukemia stem cells, featured by a symbolic cellular response of cell cycle dysregulation." (PMID 36937362, 2023). "For example, BMAL1::CLOCK recruits immune-suppressive microglia cells to the TME of glioblastoma (GBM) via transcriptional activation of the OLFML3 gene." (PMID 36937362, 2023). "Recently, circadian markers such as CLOCK and BMAL1 have been tied to immune suppression in glioblastomas by increasing microglia infiltration." (PMID 38173841, 2023). "Similar to these results, a subsequent GBM model study showed that downregulation of CLOCK or BMAL1 in glioblastoma stem cells (GSCs) induced cell-cycle arrest and apoptosis." (PMID 36430659, 2022). "In vitro studies using murine glioblastoma cells showed that administration of TMZ during peak BMAL1 expression in tumor cells can enhance its efficacy." (PMID 36291855, 2022). "We recently reported that the genome-wide BMAL1::CLOCK occupancy in glioblastoma stem cells was more expanded as compared with normal neural stem cells." (PMID 34732735, 2021). "In solid tumors, glioblastoma stem cells (GSCs) dependent on core circadian clock transcription factors, BMAL1 and CLOCK, for their cell growth, and targeting core clock factors in GSCs suppresses their tumor growth." (PMID 33816508, 2021). "Immunoblot analysis revealed that the pro-apoptotic markers BAX and cleaved caspase-3 were increased and the anti-apoptotic marker BCL-2 was decreased in BMAL1-overexpressing glioblastoma cells compared with control cells." (PMID 32231148, 2020). "CLOCK and BMAL1 knockdown decreased glioblastoma proliferation through cell-cycle arrest and apoptosis." (PMID 32631383, 2020). "Taken together, our results suggest that BMAL1 acts as an anti-cancer gene by altering the proliferation, migration, and invasion of glioblastoma cells." (PMID 32231148, 2020). "siRNA-dependent BMAL1 silencing in U87MG glioblastoma cells accelerated cell proliferation, migration, and invasion." (PMID 32231148, 2020).
glioblastoma (continued). "In summary, our results demonstrated that BMAL1 as an anti-glioblastoma gene suppresses proliferation, migration, and invasion of U87MG cells by the downregulation of cyclin B1, p-AKT, and MMP-9." (PMID 32231148, 2020). "On the other hand, adenovirus-mediated ectopic expression of BMAL1 in glioblastoma cells resulted in the inhibition of cell proliferation, migration, and invasion." (PMID 32231148, 2020). "With the same rationale as for cell proliferation in glioblastoma cells above, we examined the role of BMAL1 in the migration and invasion of glioblastoma cells with a gain of function approach." (PMID 32231148, 2020). "Normal neural stem cell growth was unaffected by CLOCK and BMAL1 knockdown, indicating that glioblastoma cells are unique in relying on these circadian transcription factors for maximum cell growth." (PMID 32631383, 2020). "Similarly, in U87MG glioblastoma cells some pro-apoptotic markers and caspase-3 were increased in Bmal1 overexpressing cells." (PMID 37504857, 2023). "Because BMAL1 knockdown in glioblastoma cells upregulates cyclin B1 expression, BMAL1 overexpression in cells might downregulate cyclin B1 expression." (PMID 32231148, 2020). "We tested whether BMAL1 could influence proliferation, migration, and invasion of BMAL1-silenced or BMAL1-overexpressing glioblastoma cells with the aid of several assays." (PMID 32231148, 2020). "Prior to investigating the role of BMAL1 in glioblastoma cells with an RNA interference (RNAi) approach, we validated whether our BMAL1 small interfering RNA (siRNA)could silence the BMAL1 gene specifically in glioblastoma cells." (PMID 32231148, 2020). "Our results suggest that BMAL1 may function as an anti-glioblastoma gene in cell growth, migration, and invasion by regulating Cyclin B, phosphorylated -AKT (p-AKT), and metalloproteinase (MMP)-9 signaling pathways." (PMID 32231148, 2020). "This would support the finding that BMAL1 drives growth and progression in glioblastoma." (PMID 32631383, 2020). "Therefore, we used these viruses in further experiments to reveal the role of BMAL1 in glioblastoma." (PMID 32231148, 2020). "In this study, we sought to determine whether an uncontrolled circadian rhythm due to abnormal expression of BMAL1, a key regulator of the circadian clock, could influence on the tumor-promoting activities of glioblastoma cells." (PMID 32231148, 2020). "Through GR signaling depending on the time of day and the clock genes Bmal1 and Cry, daily glucocorticoids have been shown to alter the growth of glioblastoma (GBM), one of the most common malignant brain tumors in adults and with a poor prognosis." (PMID 40362450, 2025). "Additionally, CLOCK and BMAL1 in GSCs play a role in immunosuppression in glioblastoma." (PMID 40046513, 2025). "In this study, authors utilize gene set enrichment analysis on patient glioblastoma samples from publicly available databases to show that angiogenesis is one of the most enriched pathways in glioblastoma tumors with high BMAL1 expression compared to those with low BMAL1 expression." (PMID 38173841, 2023). "Hence, we performed an3-(4,5-dimethylthiazol-2-yl)-2,5-diphenyltetrazolium bromide (MTT)assay to investigate whether BMAL1 knockdown could increase the division of glioblastoma cells." (PMID 32231148, 2020). "Thus, to confirm the function of BMAL1 in glioblastoma with gain of function experiments, we prepared Adenovirus-vector (Ad-Vector) and Adenovirus-BMAL1 (Ad-BMAL1) constructs and then produced high-titer adenoviruses (~1 × 109 pfu/mL) in HEK293A cells (see Materials and Methods section)." (PMID 32231148, 2020). "Thus, in a further study, we will investigate whether BMAL1 with irradiation could further suppress tumorigenesis of glioblastoma cells." (PMID 32231148, 2020).
glioblastoma (continued). "The master genes BMAL1 and CLOCK are both essential for the survival of glioblastoma CSCs, so the researchers developed a Cry activator, SHP1705, which helps inhibit BMAL1 and CLOCK transcriptional activity." (PMID 40869256, 2025). "To further probe the role of the circadian clock in treatment response, we generated CRISPR-Cas9 knockouts (KOs) of three key clock components—BMAL1, PER2, and NR1D1—in the T98G glioblastoma cell line." (PMID 41387951, 2025). "In hepatocellular carcinoma (HCC) and glioblastoma multiforme (GBM), abnormal expression of BMAL1 is significantly correlated with enhanced tumor cell proliferation capacity, increased invasive potential, and heightened migratory activity." (PMID 41228459, 2025). "Morning administration of temozolomide in glioblastoma increased OS in O6-Methylguanine-DNA-methyltransferase (MGMT) methylated patients, which was consistent with the peak expression of the clock gene BMAL1." (PMID 38585011, 2024). "For instance, in a glioblastoma study, TMZ exhibited highest anti-tumor ability when BMAL1 at daily maximum expression in vitro and in vivo." (PMID 38607733, 2024). "A notable exception is in glioblastoma stem cells (GSCs), where GSCs with amplified MYC maintained oscillation and actually relied on CLOCK and BMAL1 to maintain stemness." (PMID 37639465, 2023). "Therefore, BMAL1 may be a potential therapeutic target in the treatment of glioblastoma." (PMID 32231148, 2020). "Therefore, the BMAL1 gene could be a potential therapeutic target in the treatment of glioblastoma." (PMID 32231148, 2020). "In addition, glioblastoma cell lines (GSCs) derived from patient and human GBM cell cultures showed circadian rhythms in brain and muscle Arnt-like protein 1 (Bmal1) expression." (PMID 36556190, 2022). "For example, in glioblastoma (GBM) stem cells, acute myeloid leukemia (AML), and hepatocellular carcinoma (HCC), BMAL1 is essential for the proliferation of tumor cells." (PMID 37601651, 2023). "However, the mechanism of BMAL1 in glioblastoma has not yet been elucidated." (PMID 32231148, 2020).
depression (29 papers, 2009 to 2025). "Several studies have shown that animal models of anxiety- or depression-like phenotypes are associated with BMAL1 changes in the hippocampus." (PMID 41440117, 2025). "A long-term variable photoperiod (LVP), which causes circadian disruption in mice, induces anxiety- and depression-like behaviors accompanied by increased nocturnal expression of Bmal1 in the PFC and hippocampus." (PMID 41440117, 2025). "Studies in non‐human primates have also linked BMAL1 ablation with elevated cortisol levels and depression‐related behavior phenotypes." (PMID 39225086, 2024). "Human genetic studies have implicated BMAL1 in depression, schizophrenia, bipolar disorder as well as body mass index, blood pressure and lipid levels." (PMID 39667926, 2024). "The ARNTL/BMAL1 region has shown a borderline association with depression in MS through a GWAS that studied the genetic factors of depression in an MS cohort." (PMID 36290322, 2022). "Ablation of BMAL1 up-regulated transcriptional programs toward inflammatory and stress responses, with transcription networks associated with human sleep deprivation, major depressive disorders, and aging." (PMID 34691834, 2019). "We tested this hypothesis by assessing behaviors associated with anxiety, depression, and motor function, as well as molecular and physiological properties of MSNs in mice with a selective knockout of Bmal1 and Per2 from striatal MSNs." (PMID 35755440, 2022). "Furthermore, BMAL1-deficient monkeys exhibited anxiety and depression, consistent with their stably elevated blood cortisol, and defective sensory processing in auditory oddball tests found in schizophrenia patients." (PMID 34691834, 2019). "The rs934945 SNP might influence the interaction between PER2 and other clock genes (e.g., CLOCK, BMAL1), leading to dysregulation of the circadian network and increased susceptibility to sleep disorders when combined with psychological stressors like anxiety and depression." (PMID 40951374, 2025). "LPS triggers an “inflammatory storm” by activating microglia, disrupting the balance of circadian rhythm genes, particularly BMAL1, and promoting depression-like behavior by impairing synaptic plasticity and hypothalamic-pituitary-adrenal axis function." (PMID 40936908, 2025). "In mice with a genetic model of depression (Disc1-Q31L), which also has an abnormal stress response, a decrease in BMAL1 is shown in the hippocampal CA1 region and the lateral habenula (LHb)." (PMID 41440117, 2025). "In summary, animal studies have elucidated that BMAL1 is involved in the pathogenesis of mood disorders (mostly depression- and anxiety-like phenotypes) through dysregulation of hormonal axes, including the HPA, inflammation, and neurotransmitter systems." (PMID 41440117, 2025). "A plethora of reports highlight Bmal1’s significant role in the pathophysiology of various psychiatric disorders and neurodegenerative diseases, including depression and memory defects." (PMID 39611170, 2024). "Downregulation of Bmal1 expression in the SCN of mice induced depression- and anxiety-like behavior." (PMID 35755440, 2022). "To further explore the potential dysfunctions connected to circadian disorders due to BMAL1 deficiency, we compared blood transcriptome databases for human subjects with sleep deprivation (GSE39445), major depressive disorder (GSE76826) and aging (GSE75337)." (PMID 34691834, 2019). "In chronic sleep deprivation experiments, the expression of Bmal1, Clock, Per, and Cry genes in mice was found to be abnormal, BMAL1 gene knockout in macaques exhibits reduced sleep, as well as symptoms of anxiety and depression." (PMID 40144750, 2025). "Additionally, Bmal1 affects serotonin signaling via circadian rhythms, subsequently influencing mood and impacting depression pathogenesis." (PMID 39611170, 2024).
depression (continued). "For example, it was shown that rs7107287 polymorphism in the BMAL1 gene was associated with cyclothymic temperament, symptoms of depression and stress, and the negative impact of seasonality on well-being throughout the year in humans." (PMID 39596543, 2024). "In rodent models of depression, dysregulation of circadian gene expression has been observed, with Bmal1 and Per2 as the more affected; normal rhythms could be reinstated after imipramine or melatonin treatment." (PMID 36430520, 2022). "The main mechanism of its effect is that TPs can regulate the circadian rhythm via reversing the abnormal expression of circadian clock genes Bmal1 to relieve depression, and also regulate the intestinal microbiota to increase the number of probiotics to relieve depression." (PMID 35744797, 2022). "In addition to these functions, a growing body of evidence supports an important role of Bmal1 in neurological disorders, especially psychiatric disorders (e.g., depression, schizophrenia) and neurodegenerative pathologies (e.g., Parkinson's syndrome, Alzheimer's disease, etc.)." (PMID 36593479, 2023). "In conclusion, our study reveals the specific mechanisms of Per3 ameliorates depressive disorder through modulating NAMPT-controlled NAD+ levels and highlight a critical role for Per3 in mitochondrial energy metabolism by impacting the BMAL1 compound through the NAMPT/NAD+-SIRT3 pathway." (PMID 39894345, 2025). "We demonstrate here that the administration of the synthetic REV-ERB agonist SR1006732 causes a transient anhedonic effect in DD conditions and enhances the development and maintenance of stress-induced depression-like phenotype in the CDM in LD, whilst suppressing Bmal1 and Homer1a expression." (PMID 39179578, 2024). "Using CaMKII: CaMKII-Cre or CaMKII-tTA mice to induce specific deletion of forebrain excitatory neurons while preserving the integrity of Bmal1 in the SCN revealed significant memory impairment without anxiety or depression-like behavior." (PMID 36593479, 2023). "In addition, people with a history of depression have elevated expression of the circadian system genes CLOCK, PER1, and BMAL1 compared with healthy volunteers." (PMID 30083112, 2018). "Gsk3b destabilizes the molecular clock by promoting Bmal1 ubiquitination and subsequent degradation, and increased Gsk3b activity has been described in several psychiatric disorders with documented impairment in circadian clock function (e.g. bipolar disorder, schizophrenia, ADHD, and depression)." (PMID 37561236, 2023). "As a previous study reported that overexpression of Bmal1 can up-regulate the expression of Sirt3 and Sod2, and reduce mitochondrial dysfunction induced by 3-MCPD, in conjunction with our findings, we suspected that SIRT3 might also be involved in the development of depression modulated by Per3." (PMID 39894345, 2025).